JAG1 (jagged canonical Notch ligand 1)
Diseases named in the same sentence as JAG1 in open-access papers (continued):
Sharing a sentence is not in itself a finding about the gene and the disease.
bladder cancer (6 papers, 2014 to 2023). "Taken together, we identified the relationship between laminin, integrin, Notch, and TRB3/JAG1 in bladder cancer." (PMID 35585515, 2022). "Together, those results suggested that the activation of Notch in bladder cancer was dependent on TRB3/JAG1 signaling." (PMID 35585515, 2022). "Based on the findings and limitations of previous studies, our study sheds further light on that laminin activated TRB3/JAG1/Notch signaling through integrin α6β4 to promote bladder cancer development." (PMID 35585515, 2022). "Meanwhile, we elucidated the underlying mechanism of laminin-induced bladder cancer progression, which was dependent on an integrin α6β4/TRB3/JAG1/Notch signaling pathway." (PMID 35585515, 2022). "Given the crucial role of laminin/integrin α6β4/TRB3/JAG1/Notch in promoting bladder cancer development, it could be feasible to suppress Notch signals for improved outcome in bladder cancer treatment." (PMID 35585515, 2022). "Also, we found the activation of Notch 1 in bladder cancer is dependent on TRB3/JAG1 signaling." (PMID 35585515, 2022). "We investigated the expression levels of 5 model genes (COL5A2, JAG1, MSX1, OLR1, and STC) in normal bladder epithelial cell lines (SV-HUC-1) and bladder cancer cell lines (T24 and 5637)." (PMID 37988196, 2023). "The expression levels of 5 model genes (COL5A2, JAG1, MSX1, OLR1, and STC) were significantly increased in bladder cancer cell lines (T24 and 5637) compared with the normal bladder epithelial cell line SV-HUC-1." (PMID 37988196, 2023). "LncRNA XIST (X-inactive specific transcript) inhibits miR-124 in three types of cancer: bladder cancer, laryngeal squamous cell carcinoma, and tongue squamous cell carcinoma, which activates AR (androgen receptor), EZH2 and JAG1 (jagged 1) proteins." (PMID 36362406, 2022). "The development of bladder cancer stimulated by the laminin/integrin α6β4/TRB3/JAG1/Notch pathway could be inhibited by Notch inhibitor SAHM1, which described a new strategy in the treatment of bladder cancer." (PMID 35585515, 2022).
congenital hypothyroidism (6 papers, 2017 to 2024). A thyroid hormone deficiency present from birth. "However, congenital hypothyroidism (CH) remains uncommon in individuals with JAG1 mutations, documented in a limited 27 cases, of which 18 solely exhibited CH symptoms 21–24." (PMID 38245625, 2024).
fibrosis (6 papers, 2016 to 2022). the formation of excess fibrous connective tissue in an organ or tissue in a reparative or reactive process. "It is interesting to note that H3K79me3 occupancy on the promoter of Jag1 was markedly upregulated in TGF-β1-induced fibrosis, which was alleviated upon DOT1L inhibition with EPZ5676." (PMID 35039472, 2022). "We confirmed the higher protein expression of JAG1 and NOTCH2 in kidneys with fibrosis." (PMID 30226866, 2018).
head and neck cancer (6 papers, 2016 to 2024). A primary or metastatic malignant neoplasm affecting the head and neck. "Interestingly, we found that high JAG1 expression was associated with unfavorable prognostic outcomes in both the Taiwanese cohort (GSE37991) and the TCGA head and neck cancer (TCGA-HNSC) cohort." (PMID 35249111, 2022). "The angiogenesis-promoting activity of JAG1 has been elegantly demonstrated by showing that JAG1-expressing head and neck cancer cells triggered NOTCH activation in co-cultured endothelial cells and promoted capillary-like sprout formation in vitro and angiogenesis in vivo." (PMID 27029061, 2016).
medulloblastoma (6 papers, 2013 to 2022). A malignant, invasive embryonal neoplasm arising from the cerebellum. "Knocking down expression of JAG1 in Daoy cells, a Ptch-mutant medulloblastoma cell line, resulted in a decrease in proliferation and an increase in cleaved caspase 3/7, indicators of apoptosis." (PMID 26258793, 2015). "Regardless of molecular subgroup, human medulloblastoma samples exhibit increased expression of JAG-1, DLL-1, Hes1 and Notch2 and decreased expression of JAG-2 and DLL-4 as compared to normal cerebellum." (PMID 26258793, 2015).
muscular dystrophy (6 papers, 2016 to 2025). Muscular dystrophy (MD) refers to a group of more than 30 genetic diseases characterized by progressive weakness and degeneration of the skeletal muscles that control movement. "Notably, Jag1 overexpression rescued the muscular dystrophy phenotype of dystrophin-deficient zebrafish." (PMID 27644105, 2016). "Furthermore, a unique variant in JAG1, which is not directly related to skeletal muscle disease, has been found to possess a modifying effect on muscular dystrophy, and NEURL1 had been found to affect the signaling activity of JAG1 by directly enhancing its ubiquitination." (PMID 38296890, 2024).
Stroke (6 papers, 2011 to 2021). Sudden impairment of blood flow to a part of the brain due to occlusion or rupture of an artery to the brain. "However, in vivo experiments are warranted to demonstrate the cause effect of miR-124a through targeting JAG1 on stroke-induced neurogenesis, although our in vivo data showed that down-regulation of miR-124a by stroke was inversely correlated to upregulation of JAG1." (PMID 21887253, 2011). "Previous studies have identified several targets of miR-124, such as PTB/hnRNP I (PTBP1) and SRY-box transcription factor (Sox9), which participate in neuronal differentiation; and Jagged1 (JAG1), which mediates neurogenesis in stroke." (PMID 33841091, 2021). "Instead, our data provide several lines of evidence to demonstrate that in vitro, miR-124a mediates stroke-induced neurogenesis by targeting the JAG1 in neural progenitor cells." (PMID 21887253, 2011). "JAG1 is a ligand of the transmembrane protein Notch receptors, and the Notch signaling pathway mediates stroke-induced neurogenesis." (PMID 21887253, 2011). "Our real-time RT-PCR and Western blot analysis showed that stroke increased JAG1 mRNA and protein levels in SVZ neural progenitor cells, which was negatively correlated with miR-124a signals." (PMID 21887253, 2011). "Downregulation of miR-124a induces JAG1 expression in the SVZ neural progenitor cells after stroke and thereby promotes neural progenitor cell proliferation." (PMID 21887253, 2011). "Reduced expression of sGC, correlating with differential expression of MAML2, in stroke prone and spontaneously hypertensive rats was also seen, and RNA-Seq data demonstrated correlations between JAG1, NOTCH3, MAML2 and FRYL and the sGC subunits GUCY1A3 and GUCY1B3 in human coronary artery." (PMID 28465505, 2017). "Downregulation of miR-124 upregulates jagged 1 (Jag1), a ligand of the Notch signaling pathway, which mediates neuronal progenitor cell (NPC) proliferation leading to stroke-induced neurogenesis." (PMID 24961318, 2013). "We demonstrated that stroke altered expression profiles of multiple miRNAs in SVZ neural progenitor cells and that introduction of miR-124a inhibited ischemic neural progenitor cell proliferation and promoted the neuronal differentiation of the progenitor cells by targeting JAG1." (PMID 21887253, 2011).
cataract (5 papers, 2017 to 2025). Partial or complete opacity of the crystalline lens of one or both eyes that decreases visual acuity and eventually results in blindness. "At a gene level, JAG1 was associated with diastolic BP (p = 3.48x10-15), birth weight (p = 3.84x10-10), systolic BP (p = 3.32 x10-09) and cataracts (p = 2.21x10-04)." (PMID 33226994, 2020). "Specifically, we observed significant reductions in JAG1 and Notch receptors (Notch1, Notch2, and Notch3) in the LECs of cataract patients." (PMID 39796164, 2025).
Cirrhosis (5 papers, 2016 to 2025). A chronic disorder of the liver in which liver tissue becomes scarred and is partially replaced by regenerative nodules and fibrotic tissue resulting in loss of liver function. "Yet, we observed that Jag1, Notch 1, Notch 2, Notch 3, and Hey2 were significantly upregulated in both Ep+CIR and Ep+HCC cells as compared to Ep+NSCs, indicating the appearance of CSC like phenotype during advanced cirrhosis." (PMID 28176469, 2017).
Cognitive impairment (5 papers, 2016 to 2024). Abnormal cognition is characterized by deficits in thinking, reasoning, or remembering. "In the study of cognitive improvement by dexmedetomidine (Dex) in AD patients, the miR-129/YAP1/JAG1 axis may be a potential mechanism by which Dex protects against cognitive impairment in AD patients." (PMID 38516314, 2024).
endometrial cancer (5 papers, 2015 to 2022). Primary or metastatic malignant neoplasm involving the endometrium (mucous membrane that lines the endometrial cavity). "In the present series of patients with endometrial cancer of all types and stages we found that Notch2 and Jag1 protein expression has opposite prognostic impact." (PMID 30521558, 2018). "Our data on Jag1 expression, as an individual binary marker, reflected a favorable prognostic impact of this protein, which may be considered compatible with the proposed tumor-suppressing role of Notch pathway activation in endometrial cancer and the dual role of Notch activation in cancer." (PMID 30521558, 2018).
head and neck squamous cell carcinoma (5 papers, 2011 to 2024). A squamous cell carcinoma that arises from any of the following anatomic sites: lip and oral cavity, nasal cavity, paranasal sinuses, pharynx, larynx, and salivary glands. "Functionally, head and neck squamous cell carcinoma (HNSCC) tumors have been reported to secrete growth factors, such as HGF and TGF-α, that act in an autocrine/juxtacrine fashion to upregulate JAG1 expression through the MAKP pathway." (PMID 25309874, 2014).
Obesity (5 papers, 2021 to 2025). Accumulation of substantial excess body fat. "Given that JAG1 is linked to TNBC stemness and invasiveness and its expression in MDA-MB-231 cells is increased in response to ADS in association with BMI could reflect a new role for JAG1 in obesity." (PMID 39408921, 2024). "The latest research showed that peritumor breast adipose-derived secretome from obesity patients is a strong inducer of TNBC cell invasiveness and JAG1 expression." (PMID 41035664, 2025). "This study found that miR-204-5p inhibited adipocyte differentiation by acting on the AMPK signaling pathway and the JAG1/NOTCH3 axis, suggesting potential targets for the treatment of obesity and other related metabolic diseases." (PMID 38388551, 2024). "By contrast, ECM genes, VEGF signaling members Vegfa and Vegfc and Notch1 signaling genes Dll1, Jag1 and Numb were upregulated by sustained obesity in lung cap ECs but were not attenuated by a reversion diet." (PMID 36400935, 2022).
osteoporosis (5 papers, 2011 to 2023). A condition of reduced bone mass, with decreased cortical thickness and a decrease in the number and size of the trabeculae of cancellous bone (but normal chemical composition), resulting in increased fracture incidence. "NOTCH signaling and JAG1 expression were both impaired because of the loss of mechanical loading, but they may also be affected by the loss of miscellaneous biochemical or spatial structural signals that occurs in osteoporosis in vivo." (PMID 27171263, 2016). "In this study, we found that HDAC1 was negatively correlated with osteogenic differentiation and bone formation in the BMSCs of patients with osteoporosis, whereas jagged 1 (JAG1)-mediated NOTCH signaling was upregulated." (PMID 27171263, 2016). "Only a few osteoporosis GWAS have been reported in Asian, which have identified a few specific genes like JAG1 and ALDH7A1." (PMID 21573128, 2011). "However, we also observed that CMS modulated JAG1 expression by modifying the histone acetylation status of JAG1, as the inhibition of HDAC1 only partially rescued the mechanical unloading-induced osteoporosis in mice." (PMID 27171263, 2016).
squamous cell carcinoma (5 papers, 2013 to 2024). A carcinoma arising from squamous epithelial cells. "Here, the authors show that Jag1/2 deficiency promotes expansion of basal progenitor cells, leading to reduced squamous epithelial differentiation and enhanced formation of squamous cell carcinoma in the foregut." (PMID 38750026, 2024). "Multivariable Cox proportional hazards regression analysis showed that JAG1 transcription is associated with overall survival of squamous carcinoma (patients with high versus low JAG1 mRNA level, hazard ratio [HR] = 2.87, 95% CI = 0.99 to 8.33; p = 0.05)." (PMID 26930648, 2016). "Clinical data showed that JAG1 mRNA expression is associated with poor survival in patients with subtype squamous carcinoma of NSCLC." (PMID 26930648, 2016). "In clinical analysis, JAG1 mRNA expression was higher in tumors than in adjacent normal tissues in 14 of 20 patients with squamous cell carcinoma (SCC)." (PMID 26930648, 2016). "Next, we found that JAG1 was inclined to express in tumor parts compared with adjacent normal tissues of 14 out of 20 squamous carcinoma (p = 0.017)." (PMID 26930648, 2016). "Moreover, Jag1/2 deficiency exacerbates the deoxycholic acid (DCA)-induced squamous epithelial injury and accelerates the initiation of squamous cell carcinoma (SCC) in the forestomach." (PMID 38750026, 2024). "JAG1 and CDCP1 were mainly highly expressed in the squamous cell carcinoma group, while FAP-α was highly expressed in the adenocarcinoma group." (PMID 35054034, 2022). "JAG1 and CDCP1 were highly expressed in patients with squamous cell carcinoma, whereas FAP-α was highly expressed in patients with adenocarcinoma in our analysis." (PMID 35054034, 2022). "Moreover, JAG1 mRNA expression was analyzed in tumor tissues from 20 patients with squamous cell carcinoma (SCC), showing that increased JAG1 transcription significantly correlated with poor overall survival." (PMID 34067294, 2021).
tongue cancer (5 papers, 2018 to 2025). A malignant neoplasm affecting the tongue. "For instance, JAG1 is modulated by MALAT1/miR-125 signaling to promote tongue cancer development." (PMID 33292218, 2020). "LncRNA UCA-1 expression is induced upon TGF-β treatment in tongue cancer cells, and it promotes EMT and invasion by sponging miR-124 to promote JAG1/Notch1 signaling." (PMID 40594481, 2025).
viral infection (5 papers, 2009 to 2024). "In the context of viral infection, JAG1/Notch 1 signaling participates in the development of Th2 response in bronchial epithelial cells following infection with respiratory syncytial infection." (PMID 33883570, 2021). "Other studies have demonstrated that persistent stimulation of the NP in cultured human BMSCs through viral infection with NICD1 or JAG1 inhibited differentiation of chondrogenesis." (PMID 33512770, 2021). "Upregulation of JAG1 and DLL4 by KSHV could therefore alter the expression of cell cycle components in neighbouring uninfected cells during latent and lytic phases of viral infection, influencing cellular quiescence and plasticity." (PMID 19816565, 2009).
adrenocortical carcinoma (4 papers, 2015 to 2024). "Variations in JAG1 are associated with several types of cancers, including breast and adrenocortical cancers." (PMID 38225547, 2024). "JAG1 is the ligand for Notch1, and upregulated JAG1 promotes cell proliferation in adrenocortical carcinoma." (PMID 38474039, 2024). "Previous studies have demonstrated that increased JAG1 expression activates the Notch signaling pathway, promoting the proliferation of invasive cancer cells in adrenocortical carcinoma." (PMID 38022677, 2023).
Alagille syndrome type 1 (4 papers, 2015 to 2023). "In case NO.2, we received a definitive diagnosis of Alagille syndrome type 1 caused by heterozygous variation of the JAG1 gene, which was an autosomal dominant inheritance, and the variation came from the mother." (PMID 36797717, 2023). "For example, JAG1 gene defect causes Alagille syndrome type 1 and was also tought to be associated with hypothyroidism." (PMID 31486329, 2020). "Since mutations in JAG1 typical for Alagille syndrome type 1 have also been found in biliary atresia, we aimed to identify JAG1 mutations in newborns with proven biliary atresia (n = 72)." (PMID 26618708, 2015).
biliary atresia (4 papers, 2015 to 2024). A rare, biliary tract disease characterized by progressive obliterative cholangiopathy of the intra- and extrahepatic bile ducts, occurring in the embryonic/ perinatal period, leading to severe and persistent neonatal jaundice and acholic stool. "In contrast, the role of JAG1 mutations in aetiology of biliary atresia is still unclear." (PMID 26618708, 2015). "Mutations in JAG1 have also been found in a subset of patients with biliary atresia; however, their contribution to clinical symptoms and the disease course remains unclear." (PMID 26618708, 2015). "The pericellular fibrosis in Jag1Ndr/Ndr mice recapitulates the fibrotic phenotype of patients with ALGS and suggests that Jag1 is required for mounting a robust or rapid periportal fibrotic response, as seen in biliary atresia." (PMID 39358604, 2024). "For example, SPP1, TGFB1, JAG1, STAT1, and VIM were linked to congenital biliary atresia, and were confirmed to be strongly expressed in the endothelial and megakaryocyte." (PMID 34095116, 2021). "Likewise, the role of the JAG1 mutations in genetic aetiology of biliary atresia may be questioned." (PMID 26618708, 2015). "Our data do not support association of biliary atresia with JAG1 mutations, at least in Czech patients." (PMID 26618708, 2015). "In our cohort of 72 patients with biliary atresia of which 27 were enlisted for liver transplantation before 5 years of age, we found 5 carriers of JAG1 null mutations but no carrier of a single unique potentially pathogenic missense mutation." (PMID 26618708, 2015). "No predictably pathogenic mutations in JAG1 have been detected in the remaining 67 patients with biliary atresia by Sanger sequencing and the multiplex ligation-dependent probe amplification assay." (PMID 26618708, 2015). "In conclusion, our findings do not support association of biliary atresia with JAG1 mutations." (PMID 26618708, 2015). "Since JAG1 is not a strong biliary atresia candidate disease gene concurrent with the sporadic incidence of the disease, the reported occurrence of rare JAG1 missense mutations does not univocally prove the genotype—phenotype correlation." (PMID 26618708, 2015).
colorectal tumor (4 papers, 2018 to 2023). "In this type of colorectal tumors both receptors are activated by JAG1 and participate in blocking differentiation though HES1 but also through several other regulators such as CD44, KLR5, SOX9 and NOX1." (PMID 37860822, 2023). "Elevated Hey2, Jag1 and Notch1 expression was also observed in whole sWAT fat pads during cachexia in C26 colorectal tumor-bearing mice, showing that this genetic program is not restricted to PDAC." (PMID 37749321, 2023). "Finally, we investigated the possibility that anti-Jag1 antibodies provide a therapeutic benefit for human colorectal tumors." (PMID 30065304, 2018). "Actors of Notch signaling, such as Notch receptors (NOTCH1, -2, -3 and −4), Notch ligands (JAG1 and -2, Dll-1, -3 and4), as well as Notch pathway targets (HES and HEY effector proteins) are aberrantly overexpressed in colorectal tumors." (PMID 37860822, 2023).
congenital heart disease (4 papers, 2017 to 2024). A heart disease that is present at birth. "We describe a case of ALGS with novel mutations of JAG1 and NOTCH2 genes in a newborn girl with complex congenital heart disease, bilateral dysplastic kidneys, and malrotation with volvulus." (PMID 28465853, 2017). "Therefore, dysregulation of NOTCH signalling, such as an elevation in JAG1 levels, may lead to disorganized cardiac tissue development and ultimately result in congenital heart disease." (PMID 38647244, 2024).